GJB3 (gap junction protein beta 3)
Description:
One gap junction consists of a cluster of closely packed pairs of transmembrane channels, the connexons, through which materials of low MW diffuse from one cell to a neighboring cell.
Synonyms: Cx31; DFNA2; DFNA2B; EKV; EKVP1
Tractability: Antibody: UniProt places it where antibodies can reach, with medium confidence; UniProt predicts a signal peptide or a membrane-spanning region; its Gene Ontology location is reachable by antibodies, with medium confidence. PROTAC: ubiquitination databases record sites on it.
Gene: Protein-coding gene on chromosome 1 (34,781,214 to 34,786,369, forward strand). Ensembl gene ENSG00000188910.
Subcellular location: Cell membrane; Cell junction, gap junction
Subcellular location (Human Protein Atlas): Cell Junctions; Vesicles
Pathways (Reactome):
Developmental Biology: Differentiation of Keratinocytes in Interfollicular Epidermis in Mammalian Skin
Vesicle-mediated transport: Gap junction assembly
Gene Ontology:
Molecular function: protein binding; gap junction channel activity
Biological process: cell-cell signaling; cell communication; transmembrane transport
Cellular component: cell junction; connexin complex; gap junction; cell-cell junction; cytoplasm; plasma membrane
Genetic constraint (gnomAD): Loss-of-function variants: 8 observed, 11.29 expected, observed/expected ratio (o/e) 0.71, 90% interval 0.41 to 1.28. The upper end of that interval is the gene's LOEUF score, 1.28, which puts it in group 5 of 6, group 1 being the genes least tolerant of losing a copy. Missense variants: 348 observed, 382.23 expected, observed/expected ratio (o/e) 0.91, 90% interval 0.83 to 1. Synonymous variants: 137 observed, 163.91 expected, observed/expected ratio (o/e) 0.84, 90% interval 0.73 to 0.96.
Gene-disease validity (ClinGen):
ClinGen rates the evidence that GJB3 causes each of these diseases.
erythrokeratodermia variabilis (autosomal dominant): Definitive. A rare genetic chronic skin disorder characterized by hyperkeratosis and transient erythema.
nonsyndromic genetic hearing loss (autosomal dominant): Disputed. A disease characterized by hearing loss that is not part of a larger syndrome.
Homologues: Orthologues: macaque GJB3 (97% identical), pig GJB3 (89% identical), guinea pig GJB3 (86% identical), rabbit GJB3 (85% identical), dog GJB3 (83% identical), rat Gjb3 (83% identical), mouse Gjb3 (83% identical), tropical clawed frog gjb3 (69% identical), zebrafish gjb3 (64% identical). Paralogues in human: GJB4 (57% identical), GJB5 (51% identical), GJB7 (47% identical), GJB2 (44% identical), GJB1 (43% identical), GJB6 (41% identical), GJA1 (39% identical), GJA3 (38% identical), GJA8 (37% identical), GJA4 (37% identical), GJA9 (36% identical), GJA10 (36% identical), and 8 more.
Diseases named in the same sentence as GJB3 in open-access papers:
GJB3 is named in the same sentence as 71 diseases in open-access papers, as found by Europe PMC text mining. Sharing a sentence is not in itself a finding about the gene and the disease. The quoted sentences say what the papers report.
deafness (47 papers, 2009 to 2026). An inherited or acquired condition characterized by the complete loss of the ability to hear from one or both ears. "A total of 50 of 116 patients (43.1%) carried at least one genetic deafness-associated variant (one patient had mutations in both GJB3 and MT-RNR1)." (PMID 38172427, 2024). "The mutations of GJB3 are mainly associated with non-syndromic deafness or erythrokeratodermia variabilis." (PMID 37938151, 2023). "Another gene linked to CMT and deafness is the connexin, GJB3 (downregulated) which is a gap junction protein." (PMID 35692428, 2022). "Mutations in the GJB3 gene encoding Cx31 (e.g., in-frame 3 bp deletion: 423-425delATT) have been linked to hearing loss in Chinese families with recessive deafness." (PMID 31827424, 2019). "Mutations in the gene encoding connexin 31 (GJB3) have been detected in two different disorders: deafness and erythrokeratodermia variabilis." (PMID 25381570, 2015). "One patient (ot3285) had a heterozygous deafness mutation and a copy number reduction in the same gene (GJB3)." (PMID 25342930, 2014). "More than 10 mutations in GJB3 have been found in patients with deafness from China, Hungary, and Brazil." (PMID 23554706, 2011). "The observation that some carriers of GJB3 mutations showed a normal phenotype challenges the involvement of these mutations in dominant deafness." (PMID 19744334, 2009). "The pathogenicity of GJB3 variants is believed to lead to delayed deafness." (PMID 36847978, 2023). "Our study supports the findings that querified variants in GJB3 as a cause of deafness." (PMID 31541171, 2020). "Since GJB3 has only one coding exon, this combination may potentially result in compounded effects which cause disruption of GJB3 protein functions, leading to deafness." (PMID 25342930, 2014). "Second, since deafness is associated with GJB2 and GJB3, it should be noted that the deafness associated with the SLC26A4 gene might be a consequence of digenic inheritance." (PMID 23151025, 2012). "Further studies are required to verify whether GJB3 variants cause fully penetrant deafness." (PMID 31541171, 2020). "Common causes of deafness in SCs include mutations in genes encoding gap junction proteins, such as GJB2 (Connexin 26), GJB6 (Connexin 30), and GJB3 (Connexin 31)." (PMID 39722701, 2024). "In China, approximately 70% of hereditary deafness originates from four common deafness-causing genes: GJB2, SLC26A4, GJB3, and MT-RNR1." (PMID 38172427, 2024). "Both methods found GJB2 to be the most common deafness gene, followed by SLC26A4 and mtDNA, GJB3 variants were rare, with positive rates of 2.2%, 1.38%, 0.42%, and 0.18%, respectively, consistent with other reports." (PMID 38172182, 2024). "In the present study, 2D-PCR was used to detect the GJB2, SLC26A4, GJB3, and MT-RNR1 genes in 116 deaf patients and to explore the diagnosis rate and mutation patterns of four common pathogenic genes for deafness in Changzhou, Jiangsu, China." (PMID 38172427, 2024). "To uncover the roles of nuclear gene mutations in deafness, we screened for the mutations in common deafness-associated genes (GJB2, GJB3, GJB6 SLC26A4 and TRMU) in the matrilineal relatives of the HZD055 and HZD510 pedigrees." (PMID 36292680, 2022). "In other words, deafness can be caused by the addition of a mutation in one allele of GJB2 and one allele of GJB6 or GJB3, indicating an interaction of these connexins in the cochlea." (PMID 33126609, 2020). "It is has been shown that digenic inheritance of recessive deafness by mutations in GJB2 and GJB6, or GJB2 and GJB3 can occur." (PMID 33126609, 2020).
deafness (continued). "To examine the roles of nuclear genes (GJB2, GJB3, GJB6 and TRMU) in the phenotypic manifestation of deafness-associated 12S rRNA mutations, we carried out a mutational screening of these genes in affected matrilineal relatives of three pedigrees." (PMID 32400865, 2020). "Firstly, four common deafness‐related genes (GJB2, GJB3, SLC26A4, and mtDNA 12S rRNA) were evaluated for mutations using a microarray kit." (PMID 31250571, 2019). "The del(GJB6-D13S1830), SERPINB6, TMIE, COCH, ESPN, ACTG1, GJB3, and KCNQ4 mutations were infrequently associated with deafness in the Moravian-Silesian population." (PMID 30344259, 2018). "A hereditary deafness gene mutation screening was performed to identify the mutation sites in four deafness-related genes (GJB2, GJB3, 12S rRNA, and SLC26A4)." (PMID 28335750, 2017). "In fact, digenic inheritance of nonsyndromic deafness caused by mutations in the GJB2 gene and other connexin genes, such as GJB3, GJB6, GJB4, or GJA1, have been previously reported in several deaf patients." (PMID 25388789, 2014). "In summary, current data revealed that near half of the patients with NSHL carry deafness-causing mutation in GJB2, GJB3, GJB6, SLC26A4, or mtDNA 12SrRNA genes: 43.57% in China and 50.06% in other countries." (PMID 23554706, 2011). "During the analysis phase, the research team took altitude (low altitude, medium altitude, high altitude), ethnicity (Tibetan, Hui, Han, Salar, Tu, etc.), and genotype (15 loci of 4 common deafness-causing genes: GJB2, SLC26A4, mitochondrial 12SrRNA, and GJB3) as the core dimensions." (PMID 41734195, 2026). "The frequency of deafness gene variants in descending order was SLC26A4, GJB2, GJB3, and 12S rRNA." (PMID 41181184, 2025). "Furthermore, GJC3 (encoding Cx30.2/31.3), GJB3 (encoding Cx31), GJB1 (encoding Cx32), and GJA1 (encoding Cx43) gene mutations have been reported to cause non-syndromic deafness." (PMID 35457072, 2022). "In this observation, none of the deafness-causing GJB3 mutation was detected in both the case and control groups by sequence analysis." (PMID 23554706, 2011). "The GJB3 mutation and mtDNA 12SrRNA A1555G, however, seem not to play an important part in the causative effects of deafness in Western countries as compared with the Chinese people." (PMID 23554706, 2011). "GJB3 has been shown to be related to early-onset autosomal recessive deafness." (PMID 19744334, 2009). "Among these, a PCR hybridization screening group of 8276 neonates was tested for four deafness genes: GJB2, SLC26A4, mtDNA, and GJB3 by PCR hybridization." (PMID 38172182, 2024). "In this study, we conducted a screening of four common deafness genes (GJB2, GJB3, mitochondrial MT-RNR1, and SLC26A4) in the Chinese population to exclude mutations in these commonly associated deafness gene loci." (PMID 39020321, 2024). "For the four deafness-related genes tested, including SLC26A4, GJB2, GJB3 and mtDNA 1555 and 1494, no pathological variants were found, indicating the origin of hearing loss from the pathological nature of GA-1." (PMID 33256818, 2020). "Here, we analyzed clinical and molecular data from 21 Chinese deaf families who did not have hotspot mutations in the common deafness genes GJB2, SLC26A4, GJB3, and MT‐RNR1." (PMID 33095980, 2020). "Gene sequencing and analysis of deafness-related genes GJB2, GJB3, SLC26A4, and mtDNA did not reveal any mutation or SNPs in the patient and his mother." (PMID 31345197, 2019). "In our study, gene sequencing and analysis of deafness-related genes GJB2, GJB3, SLC26A4, and mtDNA did not reveal any mutation or SNPs in the patient and his mother." (PMID 31345197, 2019). "We performed target region capture and next generation sequencing of 127 known deafness-related genes because the individual tested negative for hotspot variants in the GJB2, GJB3, SLC26A4, and MTRNR1 genes." (PMID 30068307, 2018).
deafness (continued). "We further verified that the hearing loss could be accounted for by the p.V37I allele of GJB2, and not by other known deafness genes by targeted next generation sequencing (panel sequencing) of 82 known deafness genes (including GJB2, GJB3 and GJB6)." (PMID 23637863, 2013). "However, the lack of any functional variants in GJB2, GJB3, GJB6 and TRMU suggested that nuclear genes may not play active roles in deafness expression." (PMID 32400865, 2020).
hearing loss (39 papers, 2009 to 2025). "Further investigations on the association between hearing loss and GJB3 variants are essential in our future work." (PMID 36389375, 2022). "Mutations in Gja1 (Cx43), Gjb2 (Cx26), Gjb3 (Cx31), and Gjb6 (Cx30), which constitute gap junctions, can cause non-syndromic hearing loss." (PMID 34199197, 2021). "A few rare mutations in GJC3 (Cx30.2/Cx29) and GJB3 (Cx31) have also been linked to hearing loss but it is unclear what role these connexins play and even where these connexins are localized in the auditory tract." (PMID 32300592, 2020). "Sequence changes in GJB3 have been identified in individuals with hearing loss from several populations, but they are rare and their pathogenicity remains controversial." (PMID 20668687, 2010). "Mutations in three connexin (Cx) genes, GJB2 (Cx26), GJB6 (Cx30), and GJB3 (Cx31), have been identified and are known to cause hearing impairment." (PMID 19366456, 2009). "In our study, we targeted the limited 20 common variants in GJB2, SLC26A4, 12SrRNA and GJB3 by NGS on universal hearing loss genetic screening for newborns in Jiangxi Province, which showed the advantages of cost efficiency, high throughput and easy interpretation." (PMID 36389375, 2022). "For the first time, we analyzed the informative parameters of nine predictive in silico tools, obtained by predictions of the clinical significance of missense variants of GJB2 (Cx26), GJB6 (Cx30), and GJB3 (Cx31) connexin genes associated with hearing impairment." (PMID 31015822, 2019). "The importance of gap junctional communication for auditory function has been highlighted by the discoveries that mutations in GJB2 (coding for CX26), GJB6 (CX30) and GJB3 (CX31) may all cause hereditary hearing loss." (PMID 25381570, 2015). "Indeed, mutations in other connexin genes, such as GJB6 for Cx30 and GJB3 for Cx31, have been identified and shown to cause hearing impairment." (PMID 19744334, 2009). "Digenic inheritance of non-syndromic hearing loss caused by GJB2 and GJB3 or GJB6 has been described." (PMID 40121402, 2025). "Several susceptibility genes for hearing loss are involved in potassium recycling, such as connexin genes (GJB2, GJB3), potassium channels or channel subunits (KCNQ1, KCNQ4) and Na+/2Cl-/K+ cotransporter (SLC12A2)." (PMID 39226169, 2024). "It has been suggested that several mutations such as c.235delC in GJB2, A194T in GJB3, 150‐kb large deletion in GJB6 are the important causes for non‐syndromic hearing loss in many populations worldwide." (PMID 34811812, 2022). "Mutations in connexin genes—Cx26 (GJB2), Cx30 (GJB6), Cx29 (GJC3), Cx31 (GJB3) and Cx43 (GJA1)—have been identified as the culprits for hearing loss with distinct pathological changes in the cochlea." (PMID 33917368, 2021). "GJB3 (Gap Junction Protein β 3) and GJB6 (Gap Junction Protein β 6) are the next frequent genes that can cause hearing impairment but they are less common, with less than 10 mutations cited." (PMID 33333757, 2020). "We performed a genetic screening of GJB2 gene (responsible for the major etiologies of hereditary hearing impairment among Romanians), GJB3, GJB6, POU3F4 and WFS1 genes." (PMID 33333757, 2020). "Like DFNA2 (KCNQ4 and GJB3), DFNA5 is also predicted to be a candidate gene for age-related hearing loss (presbyacusis) since DFNA5 variation related hearing loss showed similar phenotypic with presbyacusis." (PMID 29849037, 2018). "The GJB3 gene, which is related to hereditary NSHL, was first cloned in the Chinese population, and mutations in GJB3 are associated with progressive hearing loss." (PMID 28505178, 2017).
hearing loss (continued). "We developed a PCR-reverse dot blot (RDB) assay for screening 20 hotspot mutations of GJB2, GJB3, SLC26A4, and MT-RNR1, which are common non-syndromic hearing loss (NSHL)–associated genes in the Chinese population." (PMID 28505178, 2017). "In thisstudy, we analyze nine common gene mutations (GJB2,SLC26A4, GJB3 and MT-RNR1) in 738children with severe or profound hearing loss in Inner Mongolia." (PMID 27727359, 2016). "Cx30 (GJB6), Cx29 (GJC3), Cx31 (GJB3), and Cx43 (GJA1) mutations can also cause hearing loss with distinct pathological changes in the cochlea." (PMID 26074771, 2015). "In this study, we screened the GJB2, GJB3, GJB6, SLC26A4, SLC26A5 IVS2-2A>G and mitochondrial genes to determine the etiology of hearing loss in eastern China." (PMID 23554706, 2011). "The APEX array comprises a panel of 198 sensorineural hearing loss mutations in six nuclear genes (GJB2, GJB6, GJB3, GJA1, SLC26A4 and SLC26A5) and two mitochondrial genes (MTRNR1 and MTTS1)." (PMID 20668687, 2010). "Ten patients with a family history of hearing loss showed mutations in GJB2, GJB3, GJB6, SLC26A4, mtDNA 12S rRNA, or mtDNA tRNAser(UCN) in our study population." (PMID 19744334, 2009). "It was employed for multiplex detection of 11 mutations in GJB2, GJB3, SLC26A4 and mitochondrial DNA causing hereditary hearing loss." (PMID 19366456, 2009). "To see whether nuclear genes (GJB2, GJB3, GJB6, and TRMU) mutations played active roles in clinical expression of hearing impairment, we initiated a mutational analysis of the exons of GJB2, GJB3, GJB6, and TRMU in matrilineal relatives of this pedigree." (PMID 34811812, 2022). "Furthermore, mutations in GJB2, GJB3, GJB6 and TRMU were implicated to be associated with hearing impairment." (PMID 32400865, 2020). "Other genes, such as GJB3, GJB6 and mtDNA 12SrRNA, may also play an important part in the pathogenesis of hearing loss in different countries or areas." (PMID 23554706, 2011). "Mutations in various hearing loss-related genes have been studied worldwide, and severalgenes have been identified as commonly related to hearing impairment, such asGJB2, SLC26A4, GJB3 andMT-RNR1 (mtDNA 12S rRNA gene)." (PMID 27727359, 2016). "After the systematic comparison of various genes in different countries or ethnic differences between the mutation frequencies, we calculated the average frequency of GJB2, GJB3, GJB6, SLC26A4 and mtDNA mutations in patients with nonsyndromic hearing loss." (PMID 23554706, 2011). "Moreover, no pathogenic mutation was found in the ACTG1, KCNQ4, GJB3, or COCH genes in patients with late onset hearing loss and autosomal dominant pedigrees or in patients with sporadic hearing loss." (PMID 30344259, 2018).
erythrokeratodermia variabilis (13 papers, 2008 to 2023). "GJB4 and GJB3 gene mutations can result in erythrokeratodermia variabilis (EKV), and over 20 mutations in the GJB4 and GJB3 genes have been reported to be associated with EKV." (PMID 35457072, 2022). "GJB3 was the first gap junction gene linked to hereditary skin disease and mutations cause erythrokeratodermia variabilis (EKV), a disease characterized by transient erythema and hyperkeratosis." (PMID 33807656, 2021). "Highly expressed in upper differentiating epidermis and cochlear, mutations of GJB3 can result in different diseases including erythrokeratodermia variabilis (EKV) and non-syndromic hearing loss (NSHL) ranging from profound congenital deafness to mild, progressive hearing loss in late childhood." (PMID 35677558, 2022). "Erythrokeratodermia variabilis (EKV) is an autosomal dominant disease characterized by erythematous lesions and hyperkeratosis caused by mutations in two epidermally expressed connexin genes, GJB3 (Cx31) and GJB4 (Cx30.3)." (PMID 19057675, 2008). "Mutations to GJB3, GJB4, and GJA1 are linked to erythrokeratodermia variabilis et progressiva (EKVP), a disease characterized by hyperkeratotic plaques and erythematous patches." (PMID 36861039, 2023).